TRAF6 (TNF receptor associated factor 6)
Diseases named in the same sentence as TRAF6 in open-access papers (continued):
Sharing a sentence is not in itself a finding about the gene and the disease.
Stroke (9 papers, 2015 to 2024). Sudden impairment of blood flow to a part of the brain due to occlusion or rupture of an artery to the brain. "An increasing number of studies have found that tumor necrosis factor receptor-associated factor 6 (TRAF6) is closely associated with diseases of the central nervous system, such as stroke and traumatic brain injury." (PMID 34381441, 2021). "And recently reported findings revealed that TRAF6 is distributed throughout the nervous system and plays a role in neuropathic pain, traumatic brain injuries, inflammatory responses in stroke, and neurodegenerative diseases." (PMID 38267979, 2024). "In the animal model of stroke, huc-MSCs-derived exosomes inhibit the microglia-mediated inflammatory response and promote neuronal repair via miR-146a-5p/TRAF6 axis." (PMID 35836229, 2022). "LncRNA SNHG14 induces inflammation in an in vitro stroke model by inhibiting the miR-124-3p/TRAF6 axis." (PMID 36275741, 2022). "On the other hand, data have increasingly found that TRAF6 is closely related to central nervous system diseases, such as stroke, traumatic brain injury, neurodegenerative diseases, and neuropathic pain." (PMID 34381441, 2021). "Numerous studies have reported TRAF6 upregulation associated with CNS damage due to TBI, stroke, neurodegenerative diseases, and neuropathies." (PMID 33967693, 2021). "In addition, down-regulation of LncRNA SNHG14 attenuated inflammation in an in vitro stroke model by inducing the miR-124-3p/TRAF6 axis." (PMID 36275741, 2022). "In our study, we did not observe a major involvement of TLR-4 and its downstream Traf6 signaling suggesting that CD8 could be a major upstream activator of mTOR/NF-κB in stroke." (PMID 29342151, 2018). "Here, we show that the increased expression levels of TLR2, TLR4 and TLR8, adaptor protein MyD88, signalling protein TRAF6, TLR downstream signalling proteins such as NF-κB and MAPKs were significantly prevented in IVIg-treated animals compared to control animals following stroke." (PMID 25886362, 2015).
inflammatory bowel disease (8 papers, 2013 to 2024). A spectrum of small and large bowel inflammatory diseases of unknown etiology. "A study demonstrated that two members of the TRAF family, TRAF4 and TRAF-6, were activated in patients with inflammatory bowel disease (IBD) and that both TRAF4 and TRAF-6 showed potential diagnostic value in differential diagnosis." (PMID 28219358, 2017). "TRAF6 has been found to present hypermethylation in peripheral blood mononuclear cells in inflammatory bowel disease." (PMID 31117883, 2019). "ARC modulates intestinal homeostasis and forestalls Inflammatory Bowel Disease (IBD) through TRAF6 ubiquitination and NF-κB activation in T cells." (PMID 38169510, 2024). "Inflammatory bowel disease patients exhibit upregulated ASB3 expression at focal sites, supporting the involvement of degradation of TRAF6, which promotes TLR-Myd88/TRIF-independent NF-κB aberrant activation and intestinal microbiota imbalance." (PMID 39162488, 2024). "Although it has been found that TRAF4 and TRAF6 share the same TRAF binding sites, comprehensive study of TRAF4 and TRAF6 in inflammatory bowel disease (IBD) is still lacking." (PMID 23431243, 2013).
ischemia (8 papers, 2013 to 2023). A hypoperfusion of the BLOOD through an organ or tissue caused by a PATHOLOGIC CONSTRICTION or obstruction of its BLOOD VESSELS, or an absence of BLOOD CIRCULATION. "Importantly, geniposide ameliorated the ischemia-induced upregulation of TRAF-6 and p-NF-κB significantly." (PMID 37333874, 2023). "Trans-cinnamaldehyde decreases iNOS, COX-2 expression, and NF-κB signaling pathway against neuroinflammation in ischemia/reperfusion model, and cinnamaldehyde inhibits expressions of TLR4, TNF-receptor-associated factor 6, and nuclear translocation of NF-κB in permanent MCAo model." (PMID 34257822, 2021). "In summary, our study demonstrates that exposure to PCB153 bound onto silica nanoparticles triggers TLR4/TRAF6-regulated inflammatory responses and alterations of TJ protein expression, which then contribute to enhanced brain injury following ischemia/reperfusion." (PMID 23690990, 2013). "In addition, we have also found that ischemia-induced increased expressions of TLR adaptor and signalling proteins such as MyD88 and TRAF6 were prevented by IVIg treatment." (PMID 25886362, 2015). "Thus, we selected 60 min of ischemia and 8 h of reperfusion as a point to evaluate the relationship between miR-146a and key kinases in the TLR signaling pathway, IRAK1 and TRAF6, in the murine liver during I/R injury." (PMID 24987958, 2014). "HO-1 activator CoPP can reduce the expressions of TLR2, TLR4, IRAK-4 and TRAF6, and markedly increases the expressions of TLR negative regulators, such as SOCS-1, IRAK-M and SHIP-1, in ischemia/reperfusion liver injury in rat." (PMID 29057806, 2017).
type 2 diabetes (8 papers, 2011 to 2021). "The protein levels of the TLRs, TRAF-6, MyD88, and NF-κB were significantly increased in the adipose tissue of patients with type 2 diabetes." (PMID 28219358, 2017). "Moreover, microRNA‐146a downregulation is associated with neuron apoptosis by the elevation of the protein levels of IRAK1 and TRAF6 in peripheral neuropathy and cultured dorsal root ganglia neurons in the mouse model of type 2 diabetes." (PMID 30599464, 2019).
acute lung injury (7 papers, 2019 to 2025). A condition of lung damage that is characterized by bilateral pulmonary infiltrates (pulmonary edema) rich in neutrophils, and in the absence of clinical heart failure. "It is worth noting that our study primarily focused on functional interactions of PIMT1 and TRAF6 because TRAF6 is critically implicated in LPS-induced endothelial activation and acute lung injury." (PMID 37070640, 2023). "In this study, the effects of single immunoglobin IL-1 receptor-related protein (SIGIRR) on tumor necrosis factor- (TNF-) receptor-associated factor 6 (TRAF6) ubiquitination in acute lung injury (ALI) were evaluated in both alveolar epithelial cells and alveolar macrophage cells in vitro." (PMID 33123603, 2020).
COVID-19 (7 papers, 2020 to 2025). A disease caused by infection with severe acute respiratory syndrome coronavirus 2. "TLR4 and its downstream signaling molecules, including CD14, MyD88, and TRAF6, are up-regulated in renal tubular and renal endothelial cells in COVID-19 patients, and are closely associated with acute tubular necrosis and increased kidney injury." (PMID 40584714, 2025). "FBA was also able to up-regulate the expression of genes involved in the TLR signaling pathway, such as CHUK, an inhibitor of Nf-kB, TRAF6, a mediator of the inflammatory response and Irf7, which is correlated with COVID-19 gastrointestinal symptoms." (PMID 35164139, 2022). "In platelets, TRAF6 signaling may amplify the release of inflammatory mediators, contributing to the cytokine storm observed in severe COVID-19." (PMID 40136419, 2025). "Likewise, TLR4 and its downstream elements (including Myd88, IRAK1 and TRAF6, and NF-κB - dependent genes) were significantly upregulated in PBMCs from 20 human COVID-19 patients." (PMID 38439942, 2023).
influenza (7 papers, 2013 to 2023). An acute viral infection of the respiratory tract, occurring in isolated cases, in epidemics, or in pandemics; it is caused by serologically different strains of viruses (influenzaviruses) designated A, B, and C, has a 3-day incubation period, and usually lasts for 3 to 10 days. "IL-17 signaling through the non-canonical IL-17 receptor EGFR activates the scaffold protein TRAF4 more than TRAF6 during alleviation of lung inflammation in severe influenza." (PMID 37270623, 2023). "The protein IGFALS, which distinguishes severity of WNV infection, facilitates ubiquitination of signaling mediators IRAK1 and TRAF6 to inhibit influenza viral replication and has recently been shown to be a sensitive biomarker of COVID-19 infection." (PMID 36569838, 2022). "This resulted in a network including 292 nodes that was enriched for biological pathways involved in immunoresponsiveness, including ‘Influenza infection’ and ‘TRAF6 mediated NF-kB activation’." (PMID 31931521, 2020). "For example, NLRX1 has been identified as a regulator of mitochondrial antiviral immunity through interference with RIG-I-MAVS and TRAF6-NF-kB signaling to attenuate inflammation during Sendai virus and influenza infections and LPS induced shock." (PMID 26367386, 2015). "Our results suggest that viral neuraminidase-activated TGF-β of the Th1 cells guides the Th17 evolution, and IL-17 signaling through the non-canonical IL-17 receptor EGFR activates the scaffold protein TRAF4 more than TRAF6 during alleviation of lung inflammation in severe influenza." (PMID 37270623, 2023). "Bioinformatics analysis predicted that six active compounds of CSTRG including quercetin, kaempferol, luteolin, beta-sitosterol, sitosterol, and stigmasterol could contribute to the anti-influenza activity through regulating the TRAF6/MAPK14 axis." (PMID 36452894, 2022).
lung injury (7 papers, 2018 to 2024). "In acute lung injury, kaempferol has been shown to reduce damage by altering the ubiquitination of TNF receptor-associated factor-6 (TRAF6)." (PMID 35807387, 2022). "Specifically, we found that PIMT attenuates LPS-stimulated endothelial activation and acute lung injury by inhibiting NF-κB signaling through methylation of TRAF6 and inhibition of N-glycosylation of the cell surface adhesion molecule ICAM-1." (PMID 37070640, 2023).
lupus nephritis (7 papers, 2019 to 2024). Glomerulonephritis in the context of systemic lupus erythematosus. "Inhibiting renal mesangial cells growth and inflammation by targeting TNF receptor-associated factor 6 (TRAF6) in patients with active lupus nephritis." (PMID 39835138, 2024). "It was also found that TRAF6 expression was significantly increased in patients with LN (lupus nephritis), indicating that the reduced miR-146a expression and increased TRAF6 expression may contribute to the pathogenesis of LN." (PMID 34670484, 2021). "It is reported that NEAT1 may also promote renal inflammation in lupus nephritis by upregulating the expression of TRAF6 and activating the NF-κB signaling in lupus nephritis." (PMID 34054586, 2021).
osteosarcoma (7 papers, 2013 to 2024). A usually aggressive malignant bone-forming mesenchymal neoplasm, predominantly affecting adolescents and young adults. "In addition, ATS reduced the tumour necrosis factor receptor-associated factor 6 (TRAF6)/NF-κB activity in osteosarcoma cells and the TRAF6 knockdown reduced the growth and invasion of osteosarcoma cells induced by M2 phenotype macrophages." (PMID 35989576, 2022). "All in all, the TRAF6 knockdown restrained the growth and invasion of osteosarcoma cells induced by M2 phenotype macrophages." (PMID 35989576, 2022). "On this basis, the current research demonstrated that the TRAF6 knockdown repressed the growth and invasion of osteosarcoma cells induced by M2 phenotype macrophages." (PMID 35989576, 2022). "TRAF6 (2 μg/mL) attenuated the inhibitory effect of ATS on the growth and invasion of osteosarcoma cells caused by M2 phenotype macrophages." (PMID 35989576, 2022). "Accumulated evidence suggests that TRAF6 functions as an oncogene in various malignancies including osteosarcoma." (PMID 35989576, 2022). "Subsequently, the impact of TRAF6 on the growth and invasion of osteosarcoma cells induced by M2 phenotype macrophage was evaluated." (PMID 35989576, 2022). "Specifically, miR‐146a‐5p in osteosarcoma‐derived EVs could facilitate the distant osteosarcoma metastasis by suppressing the TRAF6 expression to prevent the maturation of osteoclast." (PMID 38585233, 2024). "Thus, silencing TRAF6 in osteosarcoma, or inhibiting its expression by using its regulator miR-146b-5p, represents a potential therapeutic approach." (PMID 38534381, 2024). "In osteosarcoma cells, knockdown of TRAF6 was found to increase the apoptosis rate." (PMID 37484971, 2023). "In addition, the mechanistic results further suggest that ATS decreased the activity of TRAF6/NF-κB in osteosarcoma cells, and TRAF6 weakened the inhibitory effect of ATS on the growth and invasion of osteosarcoma cells caused by M2 phenotype macrophages." (PMID 35989576, 2022). "In general, ATS decreased the TRAF6/NF-κB activity in osteosarcoma cells." (PMID 35989576, 2022). "Moreover, the M2 phenotype macrophages transfected with si-TRAF6 were co-cultured with osteosarcoma cells." (PMID 35989576, 2022). "M2 phenotype macrophages were co-cultured with osteosarcoma cells, and the cells were treated with ATS and TRAF6." (PMID 35989576, 2022). "Meanwhile, this research further authenticated that TRAF6 attenuated the inhibitory effect of ATS on the growth and invasion of osteosarcoma cells induced by M2 phenotype macrophages." (PMID 35989576, 2022). "Overall, TRAF6 attenuated the inhibitory effect of ATS on the growth and invasion of osteosarcoma cells induced by M2 phenotype macrophages." (PMID 35989576, 2022). "In osteosarcoma, TRAF6 has been found to be upregulated when compared to normal bone tissue, and it has been related to increased cell proliferation, reduced apoptosis, and enhanced invasive capacity." (PMID 38534381, 2024). "ATS reversed M2 phenotype macrophage polarization-evoked osteosarcoma cell malignant behaviour by reducing TRAF6/NF-κB activity, suggesting ATS might be a promising drug for the clinical treatment of osteosarcoma." (PMID 35989576, 2022).
periodontitis (7 papers, 2020 to 2026). An acute or chronic inflammatory process that affects the tissues that surround and support the teeth. "Thus, this study demonstrated that A20 inhibits osteoclastogenesis through inhibition of TRAF6‐dependent autophagy in hPDLCs under hypoxic conditions, which may provide A20 as a new therapeutic target for treating bone loss in periodontitis." (PMID 32027437, 2020). "In our previous study, we found that HGF was upregulated in mice with periodontitis by aggravating the progress of periodontitis via the IL-17/RANKL/TRAF6 pathway using HGF high-expression transgenic (HGF-Tg) mice." (PMID 40427685, 2025). "IL-17 is regarded as an inducer of osteoclast differentiation via upregulating TRAF6 expression and RANKL/OPG ratio, thus enhancing bone loss in periodontitis." (PMID 41154794, 2025). "Meanwhile, RT-qPCR data revealed approximately threefold higher CD40 and TRAF6 gene expression in periodontitis compared with the healthy group." (PMID 37261283, 2023). "To investigate the variable expression of CD40 and TRAF6 in healthy individuals and patients with periodontitis, we harvested the gingival samples separately." (PMID 37261283, 2023). "Consistently, immunofluorescence staining also exhibited higher expression of CD40 and TRAF6 in the gingiva with periodontitis." (PMID 37261283, 2023). "Western blotting results further confirmed the upregulation of CD40 and TRAF6, both of which showed a nearly 1.5-fold increase in the periodontitis group." (PMID 37261283, 2023).
leukemia (6 papers, 2014 to 2025). A malignant (clonal) hematologic disorder, involving hematopoietic stem cells and characterized by the presence of primitive or atypical myeloid or lymphoid cells in the bone marrow and the blood. "To identify the basis for the reduced cell number in TRAF6-knockdown leukemia cells, we determined the effect of TRAF6 loss on apoptosis and cell cycle dynamics." (PMID 38609495, 2024). "Partial mechanistic studies reveal that pyruvate kinase isoenzyme M2 (PKM2) and TNF receptor-associated factor 6 (TRAF6) participate in the autophagic activation of leukemia cells." (PMID 36675134, 2023). "To identify the mechanism of metabolic alterations driven by TRAF6 loss in leukemia, we compared the upregulated genes in TRAF6-knockdown HEL cells (1.5-fold, P < 0.05) with the 130 previously identified essential genes for AML cell survival in vitro and in vivo." (PMID 38609495, 2024). "Therefore, we evaluated the effect of TRAF6 loss on the metabolic profiles of leukemia cells by metabolome analysis." (PMID 38609495, 2024). "Given that numerous metabolic enzymes are O-GlcNAc targets, we hypothesized that the reduction in this modification disrupts metabolic reprogramming caused by TRAF6 loss in leukemia." (PMID 38609495, 2024). "Since metabolic reprogramming is a hallmark of malignancy and crucial for supporting the heightened proliferation of tumor cells, our results imply that TRAF6 loss in leukemia cells induces metabolic alterations, contributing to their inhibited growth capacity." (PMID 38609495, 2024). "To test this hypothesis, we examined the effects of the OGA inhibitor MK8719 on the growth capacity of leukemia cells impacted by TRAF6 loss." (PMID 38609495, 2024). "In summary, our study underscores the role of TRAF6 in modulating metabolic processes and cellular dynamics in leukemia." (PMID 38609495, 2024). "Induction of shRNA targeting TRAF6 in leukemia cells resulted in the impairment of mitochondrial function as evidenced by a reduction of MMP, basal respiration, maximal respiration, and ATP production." (PMID 38609495, 2024). "We previously demonstrated that the loss of TRAF6 in BM cells with a deficiency of Tet2, which is the most frequently observed CHIP-associated mutation, results in transformation to leukemia in mice." (PMID 38609495, 2024). "This led us to investigate OGT as a mediator of TRAF6-regulated mitochondrial function in leukemia cells." (PMID 38609495, 2024). "Our findings highlight the oncogenic function of TRAF6 in leukemia and illuminate the novel TRAF6/OGT/O-GlcNAc axis as a potential regulator of metabolic reprogramming in leukemogenesis." (PMID 38609495, 2024). "These efforts will enhance our understanding of the TRAF6-OGT-O-GlcNAc axis in leukemia, potentially opening new avenues for therapeutic intervention." (PMID 38609495, 2024). "To ascertain the impact of TRAF6 loss on mitochondrial function in AML, we assessed MMP using tetramethylrhodamine-ethyl ester dye in leukemia cells." (PMID 38609495, 2024). "In contrast, mice engrafted with MLL-AF9;Traf6−/− cells developed a significantly delayed leukemia." (PMID 38609495, 2024). "Furthermore, the absence of TRAF6 in Tet2-deficient pre-leukemic cells has been shown to promote the transition to overt leukemia in mice." (PMID 38609495, 2024). "To investigate OGT’s role in the regulation of mitochondrial function mediated by TRAF6 in leukemia, we utilized a lentiviral system to overexpress OGT in TRAF6 knockdown human leukemic cells, examining its impact on growth capacity." (PMID 38609495, 2024). "However, the role of TRAF6 in leukemia cells, rather than transformation from CHIP-associated mutants, remains unclear." (PMID 38609495, 2024). "We propose that TRAF6 acts as a regulator of metabolic reprogramming, a crucial mechanism in AML progression, offering novel insights into its multifaceted role in leukemia advancement." (PMID 38609495, 2024).